EDN1 (endothelin 1)
Diseases named in the same sentence as EDN1 in open-access papers (continued):
Sharing a sentence is not in itself a finding about the gene and the disease.
pulmonary hypertension (227 papers, 1994 to 2026). Increased pressure within the pulmonary circulation due to lung or heart disorder. "The EDN1 gene encodes the endothelin 1 protein, which is associated with pulmonary hypertension, lipid metabolism, and insulin resistance." (PMID 39273477, 2024). "In line with these assumptions, the genetic deficiency of endothelin B receptor expression potentiates endothelin-1 vasoconstriction and induces pulmonary hypertension." (PMID 39452062, 2024). "An abnormal expression of EDN1 is associated with several diseases, including cardiovascular diseases, pulmonary hypertension, kidney diseases, and certain cancers." (PMID 39518808, 2024). "GS-6201 inhibited the progression of fibrotic and vascular lesions leading to pulmonary hypertension associated with endothelin-1 (ET-1) and IL-6 in interstitial lung diseases." (PMID 36901855, 2023). "The main cluster populated by the Oasl1−/−Apoe−/− mouse group (EC Sub-cluster 4) showed increased expression of genes associated with pulmonary hypertension and atherosclerosis, including Selp, Edn1, Ctla2a, Ccl2, Mmrn1, Plvap, and Lgmn." (PMID 36333342, 2022). "In subjects predisposed to high altitude pulmonary edema, endothelin-1 levels correlated with pulmonary hypertension severity." (PMID 36230894, 2022). "Our pilot study demonstrates for the first time the significance of a single minor allele adenine insertion variant in 5′UTR of edn1 gene in paediatric cases of congenital heart disease with severe pulmonary hypertension." (PMID 34011397, 2021). "Although the etiology of PVD is multifactorial, Endothelin-1 (ET-1), a potent vasoconstrictive peptide, has been implicated in the pathogenesis of pulmonary hypertension (PH) and the Endothelin-1 pathway is an important target in PH-specific drug therapy." (PMID 34011397, 2021). "Pulmonary hypertension as an effect of endotoxin challenge is a key feature during porcine endotoxemia and has been shown to partly be associated with increased endothelin-1 levels in plasma." (PMID 33926378, 2021). "The EDN1 gene encodes endothelin 1, a peptide which is a potent vasoconstrictor, the cognate receptors of which are therapeutic targets in the treatment of pulmonary arterial hypertension." (PMID 34829937, 2021). "Endothelin-1 (ET-1) is a potent vasoconstrictor regulating vascular tone and is implicated in pulmonary hypertension." (PMID 24722050, 2014). "Also, elevated plasma endothelin-1 levels have been reported to be associated with increased pulmonary hypertension, heart failure, and mortality." (PMID 40385809, 2025). "Furthermore, a correlation between pulmonary hypertension severity and endothelin-1 levels has been demonstrated in HAPE-susceptible subjects." (PMID 33578749, 2021). "The aim of present study was to explore the association of this variant with the circulating levels of Endothelin-1 in vivo using archived DNA and plasma samples from 38 paediatric congenital heart disease (cyanotic and acyanotic) patients with severe pulmonary hypertension." (PMID 34011397, 2021). "The excess of circulating endothelin-1 may be the cause of micro- and macrovascular changes and their further complications such as digital ulcers formation and pulmonary arterial hypertension frequently observed in SSc patients." (PMID 31667578, 2020). "HIF2α expression is significantly increased in cultured primary endothelial cells of Irp1-/- mice, and endothelin-1 expression is also significantly increased in lung tissues of Irp1-/- mice, supporting a pathogenic role of these molecules in the pulmonary hypertension." (PMID 24982634, 2014). "Endothelin-1 (ET-1) is a potent endogenous vasoconstrictor and is considered to contribute to the increase in vascular tone and pulmonary vascular remodelling associated with pulmonary hypertension." (PMID 25169577, 2014).
pulmonary hypertension (continued). "Endothelin-1 (ET-1) has been implicated in the pathogenesis of multiple disorders involving virtually every organ system, including congestive heart failure, pulmonary artery hypertension, atherosclerosis, cancer, autoimmune diseases, chronic kidney disease, and others." (PMID 23217151, 2012). "Interestingly, endothelin induced collagen remodeling has been reported in a mouse model of pulmonary hypertension, indicating that the increased endothelin-1 signaling in Foxf1+/− lungs may be causing an increase in collagen production." (PMID 24722050, 2014). "Preoperative plasma endothelin-1 levels are predictive of postoperative acute kidney injury (AKI), and elevated plasma endothelin-1 levels are strongly associated with pulmonary hypertension, heart failure, and mortality." (PMID 40385809, 2025). "AP-1 itself plays a crucial role in pulmonary hypertension, driving aberrant pulmonary artery smooth muscle cell proliferation via endothelin-1 signaling in idiopathic pulmonary arterial hypertension (IPAH) patients." (PMID 40501630, 2025). "There are multiple therapeutic approaches to pulmonary hypertension, some even targeting endothelin-1 signaling (by using ET receptor antagonists mainly)." (PMID 41153763, 2025). "The authors showed that belzutifan reduced the expression of both endothelin-1 and Cxcl-12, and proposed this as the mechanism of pulmonary hypertension reversal." (PMID 40806229, 2025). "Deletion of iron regulatory protein 1 in mice induces pulmonary hypertension and polycythaemia, effects that are exacerbated by low-iron intake through HIF2α and endothelin-1 upregulation in endothelial cells." (PMID 41451092, 2025). "Endothelin-1 (ET-1) is a promising biomarker for predicting BPD, as it is associated with bronchoconstriction and pulmonary hypertension, with elevated levels indicating early risk in preterm infants with nRDS." (PMID 40352605, 2025). "At the transcriptional level, GCN2/ATF4 signaling can modulate the expression of endothelin-1 (ET-1), a potent vasoconstrictor involved in pulmonary hypertension." (PMID 41511286, 2025). "The inhibition of endothelin type 1 receptors is one of the best accepted therapies in pulmonary hypertension, and reducing endothelin-1 activity reduces RVH in rats." (PMID 39452062, 2024). "The data suggest that SHRs are very sensitive to endothelin-1 but that the compensatory up-regulation of type B receptors normally prevents pulmonary hypertension." (PMID 39452062, 2024). "The growth factors, including TGF-β, platelet-derived growth factor (PDGF), endothelin-1 (ET-1), and β-catenin, have been identified as major drivers of EndMT in other disease models such pulmonary hypertension or cardiac fibrosis." (PMID 38398472, 2024). "Although various drugs targeting nitric oxide, endothelin-1 and prostacyclin pathways have been used in clinical settings, the mortality of pulmonary hypertension remains high." (PMID 37009479, 2023). "A knockin mouse model bearing the H194R mutation in the Hif2a gene displays decreased levels of hypoxia-induced pulmonary Endothelin-1 transcripts and protection against hypoxia-induced pulmonary hypertension." (PMID 37463421, 2023). "Both overexpression of prepro-endothelin-1 and rescued ETB deficiency led to pulmonary hypertension, pulmonary vascular hyperresponsiveness, and right ventricular hypertrophy with accompanying lymphocytic alveolitis." (PMID 35757687, 2022). "A few of the currently used anti-TGF-β drugs are statins for hypercholesterolaemia and endothelin-1 blockers for pulmonary hypertension." (PMID 35628346, 2022). "Several EDN1 polymorphisms strongly correlate with EDN1 expression and plasma ET-1 levels in cardiovascular and pulmonary hypertension patients." (PMID 36141455, 2022). "miRNA 130 was evident as highly significant and has been documented to promote vasoconstriction in pulmonary hypertension via deregulation of vasoactive mediators such as endothelin-1." (PMID 35860693, 2022).
pulmonary hypertension (continued). "This study aims to explore the correlation between high-sensitivity C-reactive protein (hs-CRP), interleukin-6 (IL-6), interleukin-10 (IL-10), endothelin-1 (ET-1), and chronic obstructive pulmonary disease combined with pulmonary hypertension (COPD-PH)." (PMID 35186226, 2022). "EDNRA encodes the endothelin 1 (EDN1) receptor, a gene involved in the vasoconstriction mechanism, as well as closely related to pulmonary hypertension and HIF activity, which is positively selected in Tibetan." (PMID 35087567, 2021). "Mathew R, Zeballos G, Tun H, Gewitz M. Role of nitric oxide and endothelin-1 in monocrotaline-induced pulmonary hypertension in rats." (PMID 33027370, 2020). "Plasma PlGF is elevated in SCD patients and the increase correlates with the severity of hemolysis, endothelin 1 (ET-1) expression, the occurrence of pulmonary hypertension and VOC." (PMID 33584641, 2020). "We choose to test the effects of chemerin in the presence of endothelin-1 which has been largely incriminated in the pathogenesis of pulmonary hypertension and is currently therapeutically targeted to treat the disease." (PMID 32848866, 2020). "We visualized intrapulmonary artery responses to endothelin-1 (ET-1), a key contractile mediator often elevated in pulmonary arterial hypertension, and to the thromboxane mimetic U46619." (PMID 31354700, 2019). "Excessive production of endothelin‐1 (ET‐1) has been observed in almost all forms of pulmonary hypertension." (PMID 29756391, 2018). "IUGR can lead to epigenetic changes of some related genes, eNOS, and endothelin-1 (ET-1), which make individuals hypersensitive to hypoxia, leading toward pulmonary arterial hypertension." (PMID 29615911, 2018). "Pulmonary arterial hypertension (PAH) is a highly proliferative, vascular remodelling disease leading to right heart failure and death, with endothelin-1 (ET-1) implicated as an important mediator of vasoconstriction and remodelling in this disease." (PMID 30103548, 2018). "Endothelin-1 (ET-1), a potent vasoactive peptide produced by endothelial cells and released during injurious stimuli such as pulmonary hypertension and heart failure." (PMID 28674538, 2017). "Endothelin-1 (ET-1) is a potent vasoconstrictor and is increased in lung tissue of patients with pulmonary hypertension." (PMID 29115963, 2017). "The management of patients with pulmonary arterial hypertension includes a targeted pharmacotherapeutic approach with medications that impact three key physiologic pathways: nitric oxide, prostacyclin, and the endothelin-1 pathway." (PMID 27929408, 2016). "Overexpression of endothelin-1, a vasoconstrictive peptide, is the result of the endothelial cell dysfunction observed in pulmonary arterial hypertension." (PMID 27929408, 2016). "Endothelin receptor antagonists block binding of endothelin-1 to the receptor, preventing overexpression of endothelin-1 in patients with pulmonary arterial hypertension." (PMID 27929408, 2016). "Endothelin-1 is a powerful pro-fibrotic mediator and vasoconstrictor that is elevated in pulmonary arterial hypertension." (PMID 26765263, 2016). "More importantly, our recent study has demonstrated it can mitigate pulmonary artery hypertension with attenuation of right ventricle hypertrophy by suppressing endothelin-1 (ET-1), inactivating RhoA/ROCK, and enhancing eNOS expression." (PMID 26056815, 2015). "An increased endothelin-1 mRNA level in the lungs of broilers is a common feature of natural or induced pulmonary hypertension." (PMID 24286074, 2013). "Endothelin-1 is a peptide mainly produced by endothelial cells with increased expression in pulmonary hypertension." (PMID 24286074, 2013). "In order to assess their role on pulmonary hypertension in broilers, we determined mRNA expression of genes of the TGFβ family and endothelin 1 in lung samples from 4-week-old chickens raised either under normal or cold temperature conditions." (PMID 24286074, 2013).
pulmonary hypertension (continued). "Excessive production of endothelin-1 (ET-1), a potent vasoconstrictor, occurs with several forms of pulmonary hypertension." (PMID 23029469, 2012). "EDN1 shows involvement in pulmonary hypertension, fibrosis, obstructive diseases and acute lung injury, and is also required for the normal development of several tissues." (PMID 21699702, 2011). "The best studied of these is the vasoconstrictor endothelin-1 (EDN1), which is elevated in patients with Chuvash polycythaemia and in the lungs of patients with pulmonary hypertension." (PMID 18410568, 2008). "Endothelin-1 (ET-1) and Nitric Oxide (NO) are crucial mediators for establishing pulmonary artery hypertension (PAH)." (PMID 18822124, 2008). "This pattern may reflect inflammation- and hypoxia-driven activation of endothelin-1 and the renin–angiotensin–aldosterone system, leading to significant vasoconstriction, pulmonary hypertension, and eGFR decline with evolving CKD." (PMID 41010963, 2025). "Endothelin-1 (ET-1), produced by endothelial cells, plays a role in inducing vasoconstriction and cell proliferation in the smooth muscle cells of the pulmonary artery, thereby contributing to the pathogenesis of pulmonary arterial hypertension (PAH)." (PMID 37511045, 2023). "Additionally, endothelin-1 (ET-1) is a relevant molecule that plays a crucial role in promoting hypoxia-induced pulmonary hypertension, and ET-1 is a vasoconstrictor peptide that is produced by endothelial cells." (PMID 36293512, 2022). "Additionally, Se deficient pulmonary microvascular endothelial cells exhibit increased endothelin-1 expression, which is increased in preterm infants with bronchopulmonary dysplasia and pulmonary hypertension." (PMID 36552625, 2022). "Endothelin-1 plays an important role in the regulation of pulmonary blood flow, and its enhanced production and/or decreased clearance might contribute to pulmonary hypertension." (PMID 33578749, 2021). "Endothelin-1 plays an important role in the pathogenesis of severe pulmonary hypertension." (PMID 34011397, 2021). "The activation of CD47, via TSP1, stimulates the interaction of endothelin-1 (ET-1) with endothelin receptor A, mediating proliferation and hypertrophy of pulmonary arterial smooth muscle cells as well as vasoconstriction, leading to pulmonary hypertension." (PMID 33920030, 2021). "Previous work has already presented endothelin-1, as a co-mitogenic factor potentiating growth-promoting effects of other factors and contributing to pulmonary artery remodeling in pulmonary arterial hypertension." (PMID 32848866, 2020). "Pulmonary hypertension is typically characterized by vascular remodeling and increased production of vasoconstrictors (e.g. ROS and endothelin-1), elevated pulmonary arterial smooth muscle cell [Ca2+]i levels, and enhanced sensitivity of the contractile apparatus to Ca2+." (PMID 28666030, 2017). "Moreover, strong correlation has been found in the levels of endothelin-1 and the degree of pulmonary hypertension." (PMID 28677661, 2017). "In patients suffering from pulmonary arterial hypertension, endothelin-1 (ET-1) synthesis is up-regulated and may increase PASMC activity and vessel wall remodeling through transforming growth factor beta-1 (TGF-β1) and connective tissue growth factor." (PMID 24015303, 2013). "Our previous studies have revealed that iptakalim could alleviate pulmonary artery remodeling and pulmonary hypertension in chronic hypoxic rats and inhibit the proliferation of rabbit or human PASMCs induced by endothelin-1 (ET-1)." (PMID 23554716, 2011). "Endothelin-1 signalling plays an important role in pathogenesis of pulmonary hypertension." (PMID 21699729, 2011). "• Endothelin-1 levels correlate with the magnitude of pulmonary hypertension." (PMID 18954441, 2008).
pulmonary hypertension (continued). "In animal models of pulmonary hypertension, overexpression of the A2BAR has been associated with increased levels of remodelling agents (e.g., IL-6 and matrix metalloproteinases) and signalling molecules implicated in the pathogenesis of PAH, such as endothelin-1." (PMID 37402944, 2024). "In addition, in a subsequent study, chronic expression of endothelin-1 was related to progressive pulmonary fibrosis associated with inflammatory cell infiltration, but interestingly, did not result in significant pulmonary hypertension." (PMID 35629370, 2022). "The endothelin system is well known to be involved in sepsis, as endothelin-1 (ET-1) induces activation of NF-κB-mediated proinflammatory pathways and expression of adhesion molecules and ET-1 levels appear increased in septic newborns, particularly in case of pulmonary hypertension." (PMID 30174784, 2018). "An augmented release of endothelin-1 and/or its reduced pulmonary clearance in HAPE-susceptible mountaineers was hypothesized to represent one of the mechanisms contributing to exaggerated pulmonary hypertension at high altitude." (PMID 24465776, 2014). "Ambrisentan, which is meant to block the action of endothelin-1 at the ETA receptor, has been approved for the treatment of pulmonary arterial hypertension." (PMID 30809542, 2019). "Endothelial Functions. miR-98, which is reduced in endothelial cells of patients suffering from idiopathic pulmonary hypertension (IPAH) and of mouse models of this disease, directly targets endothelin-1 (ET1)." (PMID 28167956, 2017). "Liu and colleagues found that EP ameliorates monocrotaline-induced pulmonary arterial hypertension and reverses pulmonary vascular remolding in rats by inhibiting the release of TNF-α and IL-6 and by reducing the expression of endothelin-1." (PMID 25470819, 2014). "In pulmonary arterial hypertension (PAH), increases in endothelin-1 (ET-1) contribute to elevated pulmonary vascular resistance which ultimately causes death by right ventricular heart failure." (PMID 24582810, 2014). "In pulmonary arterial hypertension (PAH), increases in endothelin-1 (ET-1) contribute to elevated pulmonary vascular resistance which ultimately causes death by right ventricular (RV) heart failure." (PMID 24582810, 2014). "Furthermore, increased endothelin-1 (ET-1) levels in COPD patients, especially during exacerbations, contribute to pulmonary hypertension by promoting vasoconstriction and vascular remodeling." (PMID 39337534, 2024). "In pulmonary hypertension, hypoxia increases mitochondrial ROS generation and stimulates the activation of hypoxia-inducible factor (HIF)-1α-endothelin 1 (ET-1) axis leading to hypoxic vasoconstriction, thereby increasing pulmonary pressure and right heart load." (PMID 30081534, 2018). "As in this study, increased endothelin 1 mRNA levels have been previously reported in the lungs of broilers with natural or induced pulmonary hypertension compared to nonpulmonary hypertensive broilers." (PMID 24286074, 2013). "The present study was designed to investigate endothelin-1 and NO concentration in the exhaled breath, as well as circulating levels of ET-1 in COPD patients with or without pulmonary hypertension." (PMID 18822124, 2008). "The role of endothelin-1 in the development of pulmonary hypertension and right heart hypertrophy is further substantiated by the fact that several ETA antagonists such as bosentan, macitentan and ambrisentan have been shown to produce beneficial effects in patients with pulmonary hypertension." (PMID 38786079, 2024). "Although we could not directly prove whether SHRs* have pulmonary hypertension, increased endothelin-1 and ACTA2 expression predicts an increase in RV afterload and subsequent RVH." (PMID 39452062, 2024).
pulmonary hypertension (continued). "Norepinephrine may crosstalk with 5-HT to superimpose SAM on idiopathic pulmonary hypertension and PPHN, with histamine to create and add eosinophils to SCAD and with endothelin-1 to generate a field effect that forms a venous angiopathy terminating as venous FMD." (PMID 34881056, 2021). "Endothelin-1, a potent vasoconstrictor and HIF target, is significantly increased in Chuvash mice and could be a downstream effector molecule in the pathogenesis of pulmonary hypertension." (PMID 24982634, 2014).